RNU6-538P (RNA, U6 small nuclear 538, pseudogene)
Gene: Small nuclear RNA gene on chromosome 9 (66,142,221 to 66,142,327, reverse strand). Ensembl gene ENSG00000275030.
Homologues: Orthologues: chimpanzee U6 (99% identical), macaque U6 (93% identical), dog U6 (70% identical), mouse Gm54642 (61% identical), mouse Gm22279 (59% identical), rat LOC120101210 (58% identical). Paralogues in human: RNU6-1193P (100% identical), RNU6-1269P (100% identical), RNU6-368P (100% identical), RNU6-1320P (99% identical), RNU6-599P (99% identical), U6 (97% identical), U6 (96% identical), RNU6-316P (95% identical), RNU6-55P (95% identical), U6 (95% identical), RNU6-954P (94% identical), RNU6-821P (87% identical), and 1288 more.